PI16 (peptidase inhibitor 16)
Description:
May inhibit cardiomyocyte growth.
Synonyms: CD364; CRISP9; PSPBP; MGC45378; dJ90K10.5; MSMBBP
Tractability: Antibody: UniProt places it where antibodies can reach, with high confidence; UniProt predicts a signal peptide or a membrane-spanning region; its Gene Ontology location is reachable by antibodies, with medium confidence. PROTAC: ubiquitination databases record sites on it.
Gene: Protein-coding gene on chromosome 6 (36,948,263 to 36,965,993, forward strand). Ensembl gene ENSG00000164530.
Subcellular location: Secreted
Gene Ontology:
Molecular function: protein binding
Cellular component: extracellular region
Genetic constraint (gnomAD): Loss-of-function variants: 35 observed, 38.04 expected, observed/expected ratio (o/e) 0.92, 90% interval 0.7 to 1.22. The upper end of that interval is the gene's LOEUF score, 1.22, which puts it in group 5 of 6, group 1 being the genes least tolerant of losing a copy. Missense variants: 572 observed, 609.28 expected, observed/expected ratio (o/e) 0.94, 90% interval 0.88 to 1.01. Synonymous variants: 275 observed, 257.28 expected, observed/expected ratio (o/e) 1.07, 90% interval 0.97 to 1.18.
Homologues: Orthologues: chimpanzee PI16 (99% identical), macaque PI16 (96% identical), dog PI16 (76% identical), pig PI16 (73% identical), mouse Pi16 (66% identical), rat Pi16 (65% identical), guinea pig PI16 (60% identical).
Diseases named in the same sentence as PI16 in open-access papers:
PI16 is named in the same sentence as 51 diseases in open-access papers, as found by Europe PMC text mining. Sharing a sentence is not in itself a finding about the gene and the disease. The quoted sentences say what the papers report.
heart failure (4 papers, 2013 to 2025). Inability of the heart to pump blood at an adequate rate to meet tissue metabolic requirements. "PI16 is also strongly upregulated in human and rodent models of heart failure, where it accumulates in the intercellular space and inhibits murine cardiomyocyte growth." (PMID 27996045, 2016). "Pi16 is a known regulator of cardiac hypertrophy and is upregulated in hypertrophy and heart failure." (PMID 23724005, 2013). "However, the initial active player M_SH, co-expressing Ackr3, Cd34, Cd248, and Pi16, was reported as cardiac mesenchymal-like stem cells with multilineage differentiation and self-renewal capacities, and promoted heart failure." (PMID 37147443, 2023). "Another study demonstrated that the expression of the peptidase inhibitor 16 (PI16) protein is increased in heart diseases such as myocardial infarction and heart failure." (PMID 40660005, 2025).
prostate carcinoma (4 papers, 2012 to 2023). A carcinoma that arises from epithelial cells of the prostate gland. "Studies have shown that PI16 is involved in extracellular matrix regulation, acts as a tumour suppressor gene and is a new independent prognostic marker of prostate cancer." (PMID 37525118, 2023). "Decrease of PI16 level was detected in prostate cancer and gastric cancer." (PMID 22496748, 2012). "Our result also showed that the expression of PI16 in colorectal adenocarcinoma was significant decreased compared with the adjacent non-tumor colorectal tissue, which was consistent with the result of the research in prostate cancer and gastric cancer." (PMID 22496748, 2012).
cardiac hypertrophy (3 papers, 2013 to 2020). "Using the Ang II–induced cardiac hypertrophy and fibrosis model, we found that PI16 overexpression inhibited cardiac hypertrophy and collagen synthesis induced by Ang II." (PMID 32227584, 2020). "Generally, PI16 is a HDAC1 regulator specifically in CFs, and PI16 overexpression prevents cardiac hypertrophy and fibrosis by inhibiting stress‐induced CF activation." (PMID 32227584, 2020). "Pi16 gene which is involved in the regulation of peptidase activity biological process and cardiac hypertrophy was also upregulated in PAI-1 knockout hearts compared to wildtype controls." (PMID 23724005, 2013). "However, the role of PI16 in CFs during pathological cardiac hypertrophy and fibrosis remains unknown." (PMID 32227584, 2020). "Echocardiography at 4 weeks after Ang II treatment showed that PI16 overexpression decreased the degree of cardiac hypertrophy, but not left ventricle systolic function." (PMID 32227584, 2020). "By contrast, our study showed that direct overexpression of PI16 with an adenovirus vector in CMs exhibits no anti‐hypertrophic effect on Ang II treatment, which is not consistent with the reduced cardiac hypertrophy found in PI16‐Tg mice." (PMID 32227584, 2020). "Protease inhibitor 16 (PI16) is a protein secreted by cardiomyocytes and it might elicit inhibitory effects on myocardial hypertrophy." (PMID 29744364, 2018).
colorectal cancer (3 papers, 2012 to 2025). A primary or metastatic malignant neoplasm that affects the colon or rectum. "The association of ITGBL1 with ECM remodeling and immune evasion has been reported in ovarian and colorectal cancers, whereas PI16 has been implicated in fibrotic diseases and the activation of tumor-associated fibroblasts." (PMID 41246350, 2025). "Since PI16 is not well characterized and so far there is no report whatsoever about PI16 in colorectal cancer etiology, our result implied that PI16 may become a promising biomarker for colorectal cancer early diagnosis." (PMID 22496748, 2012).
gastric cancer (3 papers, 2012 to 2025). A primary or metastatic malignant neoplasm involving the stomach. "Another cell compendium of cross-tissue fibroblast, described steady-state fibroblast, positive for PI16 and COL15A1, which were strikingly similar to resting fibroblast in our gastric cancer data." (PMID 36550535, 2022). "Our analysis revealed dynamic remodeling of the tumor microenvironment during gastric cancer progression, characterized by the expansion of dysfunctional CD8+ T cells, pro-tumorigenic fibroblasts (e.g., ITGBL1+, PI16+, and ITLN1+), and altered myeloid populations." (PMID 41246350, 2025).
atherosclerosis (2 papers, 2021 to 2025). A disease characterized by the build-up of fatty material and calcium deposition in the arterial wall resulting in partial or complete occlusion of the arterial lumen. "It has been shown that while PI16 plays a protective role against atherosclerosis, these results demonstrate the pathogenesis of cardiac maladies in severe COVID-19 patients." (PMID 33995121, 2021). "Rare cells expressing FB-like (I-cluster 12, Pi16+, Igfbp4+, and Dpep1+) or MΦ-like genes (I-cluster 14, Lgals3+, Cd68+, and Ptprc+) had low expression of the eYFP lineage label, suggesting that these cells were not derived from VSMCs, similar to what has been proposed in atherosclerosis." (PMID 40577585, 2025).
autoimmune disease (2 papers, 2023 to 2024). A disorder resulting from loss of function or tissue destruction of an organ or multiple organs, arising from humoral or cellular immune responses of the individual to their own tissue constituents. "And PI16 may be one of the underlying mechanisms contributing to immune cell dysfunction in patients diagnosed with autoimmune diseases." (PMID 38566233, 2024). "PI16 is an inhibitor of T cell surface protein peptidase, and its downregulation indicates immune tolerance damage in the body, which may increase the risk of autoimmune diseases." (PMID 36178657, 2023). "Targeting PI16 may facilitate Treg cell-based therapies for preventing autoimmune diseases and inflammatory diseases." (PMID 38566233, 2024).
colitis (2 papers, 2024). Inflammation of the colon. "The AIA model of PI16CKO is characterized by the reduction of joint structure and the attenuation of synovial inflammation and in DSS-induced colitis model, conditional knockout of the PI16 reduce intestinal structural damage." (PMID 38566233, 2024). "In conclusion, our data have disclosed a previously unreported new function of PI16 in regulating Treg differentiation and function, which will contribute to arthritis and colitis development." (PMID 38566233, 2024). "Single-cell transcriptomic profiling of chronic dextran sulfate sodium salt murine colitis model revealed that CD81+Pi16– fibroblasts exhibited transcriptomic and functional similarities to human FAP+ fibroblasts." (PMID 39024569, 2024). "In the current study, we have found conditional knock-out PI16 in Tregs can significantly promote the differentiation and functions of Tregs and suppress autoimmune arthritis (AIA) and dextran sulfate sodium (DSS)-induced colitis development." (PMID 38566233, 2024).
colon cancer (2 papers, 2020 to 2022). "PI16 is a peptidase inhibitor; consistent with our findings, other studies have detected decreased expression of PI16 in colon cancer." (PMID 32321427, 2020).
hepatocellular carcinoma (2 papers, 2020 to 2025). A malignant tumor that arises from hepatocytes. "Against this and more in line with our observations,increased expression of PI16 has been observed in other cancers, forexample, hepatocellular carcinoma (HCC)." (PMID 41181894, 2025).
ovarian carcinoma (2 papers, 2017 to 2023). A malignant neoplasm originating from the surface ovarian epithelium. "In the ovarian cancer case study the method revealed the two additional genes characteristic for the cellular quiescence: PI16 and WNT7A." (PMID 29362714, 2017).
abdominal hernia (1 paper, 2021). "The overexpression of PI16 inhibits MMP activity, and MMPs, including MMP1, MMP2, MMP9, and MMP13, are associated with abdominal hernia development." (PMID 34341761, 2021).
Aortic dissection (1 paper, 2022). Aortic dissection refers to a tear in the intimal layer of the aorta causing a separation between the intima and the medial layers of the aorta. "Nine proteins (Lumican, FGL1, PI16, MMP9, FBN1, MMP2, VWF, MMRN1, and PF4) related to the pathogenesis of aortic dissection were identified by David /Ease and String techniques as candidate biomarkers for verification test." (PMID 35910577, 2022).
Arthritis (1 paper, 2024). Inflammation of a joint. "Upon removal of the PI16 gene in Treg cells, there was a notable reduction in both bone destruction and synovial swelling in arthritis, accompanied by a less severe manifestation of immune disorders." (PMID 38566233, 2024).
bladder cancer (1 paper, 2023). "PI16 expression was downregulated in bladder cancer tissues, and lower PI16 levels correlated with disease progression and poor survival in patients with BLCA." (PMID 37525118, 2023).
cholesteatoma (1 paper, 2023). A pathologic process characterized by the proliferation of keratinizing squamous epithelium resulting in the accumulation of keratin and cells in the middle ear and/or mastoid. "Additionally, universal fibroblast marker gene PI16 mRNA expression was decreased by proinflammatory cytokines, suggesting that inflammatory cytokines cause differentiation from human skin fibroblasts with general characteristics to cholesteatoma-specific fibroblasts expressing high levels of INHBA." (PMID 37537159, 2023).
Cognitive impairment (1 paper, 2021). Abnormal cognition is characterized by deficits in thinking, reasoning, or remembering. "Cognitive impairment may be associated with hernia development by downregulating miR-4451 to upregulate PI16." (PMID 34341761, 2021).
dementia (1 paper, 2021). Loss of intellectual abilities interfering with an individual's social and occupational functions. "We also found that miR-4451 regulates the PI16 expression, which may be a key target and biomarker for hernia pathogenesis and dementia crosstalk." (PMID 34341761, 2021). "miR-4451 may inhibit PI16 transcription, which may be a potential link between herniation and dementia development." (PMID 34341761, 2021).
diabetic nephropathy (1 paper, 2023). "The genes that contributed to the biological relevance of diabetic nephropathy, include gene TTN (rs72646845), PI16 (rs113848006), DPY6 (rs36027551), CROCC (rs41272737), PPP1R3A (rs1799999), ZNF136 (rs140861589), HSPA12B (rs6076550), and FRMD4A (rs1541010)." (PMID 37033211, 2023).
Hernia (1 paper, 2021). "In clinical samples, PI16 was found to be upregulated in hernia, while miR-4451 was found to be downregulated." (PMID 34341761, 2021). "In clinical samples, PI16 was found to be upregulated in hernia, while miR-4451 was downregulated." (PMID 34341761, 2021). "We hypothesized that miR-4451 may be involved in hernia pathogenesis by regulating PI16 transcription." (PMID 34341761, 2021). "The luciferase reporter gene assay revealed that downregulation of circulating miR-4451 may be responsible for the upregulated PI16 expression in hernia sacs." (PMID 34341761, 2021). "PI16 was found to be upregulated in hernia (p < 0.01) while miR-4451 was downregulated (p < 0.01)." (PMID 34341761, 2021).
infarction (1 paper, 2024). A localised pathological necrosis of tissue resulting from obstruction of the blood supply usually by a thrombus, an embolus, or vascular torsion. "In contrast, the downregulation of proteins such as ACTN1, MYL9, CSRP1, COMP, and PI16, which are closely associated with muscle cell development and contractility, suggests a disruption in muscular and structural integrity within the heart in the acute phase post-infarction." (PMID 39513871, 2024).
inflammatory bowel disease (1 paper, 2024). A spectrum of small and large bowel inflammatory diseases of unknown etiology. "Next, we confirmed the role of PI16 on inflammation response in another model of dextran sulfate sodium salt (DSS) induced ulcerative colitis model, a mouse model of inflammatory bowel disease (IBD)." (PMID 38566233, 2024).
keloid (1 paper, 2023). An irregularly shaped, elevated mark on the skin caused by deposits of excessive amounts of collagen during wound healing. "Immunolabelling of PI16 in human keloid and healthy dermis and hypodermis corroborated that PI16 protein expression was restricted to fascia connective tissue in the hypodermis and was absent in dermis or keloid lesions." (PMID 37968392, 2023).
lung carcinoma (1 paper, 2024). "A recent study demonstrated that CAFs expressed high levels of PI16 and CD34 localized to the blood vessel adventitia in lung cancer." (PMID 39334513, 2024).
Myocardial fibrosis (1 paper, 2024). "Similar to the human data, we also found that one subset of fibroblasts (Cluster 7) displayed heightened expression of several progenitor cell markers, such as Cd34, Ly6a, Pi16, and Thy118, in mice, suggesting that Cd34-high fibroblasts may have distinct functions in myocardial fibrosis." (PMID 39198543, 2024).
Nephropathy (1 paper, 2023). A nonspecific term referring to disease or damage of the kidneys. "While gene PI16, DPY6, FRMD4A and CROCC have not been reported to be associated with nephropathy, they have been identified in T2DM and obesity-related traits." (PMID 37033211, 2023).
osteoarthritis (1 paper, 2024). A noninflammatory degenerative joint disease occurring chiefly in older persons, characterized by degeneration of the articular cartilage, hypertrophy of bone at the margins and changes in the synovial membrane. "We previously showed that PI16 was highly expressed in RA patients' serum, synovial fluid, and synovial tissue compared to these in osteoarthritis patients and health controls." (PMID 38566233, 2024).
scleroderma (1 paper, 2023). Scleroderma is a rare autoimmune connective tissue disorder characterized by abnormal hardening of the skin and, sometimes, other organs. "In the skin, this transcriptional signature was observed in fibroblasts from unwounded skin responsible for ECM homeostasis and in a fibroblast population that undergoes contraction in scleroderma as compared to healthy skin (PI16+MFAP5+PCOLCE2+)." (PMID 37277655, 2023).
tonsillitis (1 paper, 2023). Inflammation of the tonsillar tissue. "Next, we sorted PI16+ RCs and TRCs as a control population from adult patients with OSA and tonsillitis and stimulated the in vitro cultured FRC subsets with TGF-β1, TGF-β3, LIGHT or FGF2." (PMID 37202490, 2023).
vitamin D deficiency (1 paper, 2023). A nutritional condition produced by a deficiency of VITAMIN D in the diet, insufficient production of vitamin D in the skin, inadequate absorption of vitamin D from the diet, or abnormal conversion of vitamin D to its bioactive metabolites. "Moreover, vitamin D deficiency resulted in the abnormal expression of 56 differential proteins, among which the expression levels of complement factor B, complement component C9, inducible co-stimulator ligand, and peptidase inhibitor 16 significantly changed with the decrease in vitamin D content." (PMID 36178657, 2023). "The results showed that vitamin D deficiency led to the abnormal expression of CFB, TPM4, C9, ICOSL, and PI16." (PMID 36178657, 2023). "In the present study, vitamin D deficiency downregulated the expression levels of ICOSL and PI16." (PMID 36178657, 2023).